HMGB1 (high mobility group box 1)
Diseases named in the same sentence as HMGB1 in open-access papers (continued):
Sharing a sentence is not in itself a finding about the gene and the disease.
Sepsis (continued). "To gain insight into its protective mechanism, we evaluated the effects of fetuin-A on systemic accumulation of HMGB1 during a late stage of endotoxemia and sepsis." (PMID 21347455, 2011). "Tracey and collaborators detected HMGB1 in the serum of septic patients and found that application of anti-HMGB1 antibodies reversed established sepsis." (PMID 21507210, 2011). "In one study, the circulating blood of patients with pneumonia and with pneumonia combined with serious sepsis showed greatly elevated levels of HMGB-1." (PMID 21507210, 2011). "It is thus plausible that IFN-γ, a proinflammatory cytokine predominantly derived from spleen, contributes to lethal endotoxemia or sepsis partly by stimulating HMGB1 release and partly by inhibiting hepatic fetuin-A expression." (PMID 21347455, 2011). "Lastly, supplementation of fetuin-A resulted in significant reduction of circulating HMGB1 levels during endotoxemia and sepsis." (PMID 21347455, 2011). "In 1999, during a course of experiments designed to identify late-acting mediators of endotoxaemia and sepsis, it was discovered that activated macrophages secrete HMGB1 as a delayed mediator of inflammation." (PMID 21887276, 2011). "GM-CSF treatment for sepsis-induced immunosuppression induces a moderate but only transient increase in systemic HMGB-1 levels." (PMID 20652004, 2010). "Sepsis is a major example of severe inflammatory disease in which a vicious cycle involving HMGB-1 is implicated and elevated serum levels of HMGB-1 correlate with a worse prognosis in patients with sepsis." (PMID 21092200, 2010). "Here we demonstrate that immunostimulatory treatment using GM-CSF for sepsis-induced immunosuppression induces a moderate but only transient increase in HMGB-1 levels." (PMID 20652004, 2010). "In looking for anti-inflammatory therapeutic strategies, we have also found ethyl pyruvate and alpha7nAcChR agonist choline posses a potential inhibition of HMGB1 leading to improvement of animal survival after hemorrhage or sepsis." (PMID 20628562, 2010). "It has been demonstrated that high mobility group box 1 (HMGB1) protein is an important late-phase mediator in the pathogenesis of sepsis." (PMID 23554654, 2010). "For example in vivo treatment with nicotine can inhibit TNFα-induced HMGB1 secretion and has a proven therapeutic benefit in models of sepsis." (PMID 20379354, 2010). "In sepsis, HMGB-1 is typically released by activated innate immune cells in the later phase of the disease." (PMID 20652004, 2010). "Due to a rather “wide” therapeutic window, blockade of HMGB-1 is currently investigated in patients with “late” sepsis." (PMID 20652004, 2010). "HMGB1 appears to be necessary and sufficient mediator for the severe sepsis because systemic HMGB1 is found in patients and experimental animals with severe sepsis." (PMID 20628562, 2010). "It has recently been demonstrated that the HMGB1 protein is an important late-phase mediator in the pathogenesis of sepsis." (PMID 23554654, 2010). "Administration of polyclonal anti-HMGB1 antibodies or the DNA-binding A box of HMGB1, a competitive inhibitor of the pro-inflammatory B box, can reverse the lethality of established sepsis and ameliorate collagen-induced arthritis in rodents." (PMID 20706656, 2010). "Administration of recombinant HMGB1 to mice recapitulates the characteristic organ dysfunction of severe sepsis, including derangement of intestinal barrier function, acute lung injury, and lethal multiple organ failure." (PMID 20628562, 2010). "Neutralizing antibody represents a therapeutic agent which makes HMGB1 an effective target to reverse the established sepsis in a clinically relevant time." (PMID 20628562, 2010). "In a LPS-induced sepsis model, one of the anti-HMGB1 clones, 3E8, was tested for in vivo-neutralizing activity." (PMID 19564921, 2009). "The release of HMGB1 is clinically relevant as it has been shown to be a significant contributor to late sepsis and septic shock." (PMID 19609357, 2009).
Sepsis (continued). "In humans, plasma levels of HMGB1 have been shown to be elevated in ICU patients with sepsis and patients after major surgery (esophagectomy)." (PMID 19887013, 2009). "Although the extracellular release of HMGB1 has been reported by several investigators in patients with infection and sepsis, only one study has described HMGB1 release in plasma in a small group of patients several hours after trauma." (PMID 19887013, 2009). "HMGB1 is a proven therapeutic target in experimental models of ischemia, acute respiratory distress syndrome, rheumatoid arthritis, sepsis, and cancer." (PMID 19564921, 2009). "Several studies have now been published on HMGB1 and infection, and the general consensus is that HMGB1 levels are increased in patients with sepsis as compared with healthy control individuals." (PMID 18577209, 2008). "Systemic inflammatory mediators, including high mobility group box 1 (HMGB1), play an important role in the development of sepsis." (PMID 18380908, 2008). "Different modes of HMGB1-blocking therapy, including neutralising antibodies, antagonistic truncated HMGB1, soluable RAGE (sRAGE), thrombomodulin or nuclear HMGB1 sequestration, have been successfully applied in studies of experimental arthritides and sepsis." (PMID 18346273, 2008). "The relatively low number of patients included in the present study is an obvious weakness, calling for further studies to confirm to what extent the genetic polymorphisms in the HMGB1 gene can be utilised as severity markers in SIRS and sepsis." (PMID 18577209, 2008). "HMGB1 acts as a late mediator of sepsis, detectable in septic mice after 8 hours and reaching peak levels after 16 hours." (PMID 18577209, 2008). "High mobility group box 1 protein (HMGB1) is a pleiotropic cytokine, recently implicated in the pathophysiology of the systemic inflammatory response syndrome (SIRS) and sepsis." (PMID 18577209, 2008). "Administration of recombinant HMGB1 to mice recapitulates many clinical signs of sepsis, including fever, derangement of intestinal barrier function, and tissue injury." (PMID 17987129, 2007). "In a prospective observational study, HMGB1 and several other cytokines were measured over several days in patients who had different degrees of sepsis and who were admitted to intensive care units." (PMID 17346334, 2007). "Disappointing results in trials trying to suppress early proinflammatory pathways in sepsis have made HMGB1 an interesting target molecule in sepsis." (PMID 17625012, 2007). "In light of the capacity of EGCG in inhibiting LPS-induced HMGB1 release and cytokine activities, we explored its efficacy in animal models of lethal endotoxemia and sepsis (induced by cecal ligation and puncture)." (PMID 17987129, 2007). "Our study data suggest that HMGB1 levels are much lower in patients in the milder end of the sepsis spectrum." (PMID 17346334, 2007). "In a cohort of patients with suspected community-acquired infections and sepsis, HMGB1 levels were statistically significantly higher in patients compared to the healthy controls." (PMID 17346334, 2007). "• In a cohort of patients suspected of having community-acquired infections and sepsis, levels of HMGB1 were statistically significantly higher in patients compared to the healthy controls." (PMID 17346334, 2007). "In the study by Wang and colleagues, patients with fatal sepsis had median HMGB1 levels of 84 ng/ml and surviving sepsis patients had median HMGB1 levels of 25 ng/ml." (PMID 17625012, 2007). "HMGB-1 has been recently identified as a potent pro-inflammatory mediator in sepsis and hepatic I/R injury." (PMID 17520028, 2007). "In this study, we evaluated the capacity of tea catechins in inhibiting endotoxin-induced HMGB1 release and/or cytokine activities, and explored their therapeutic potential in animal model of sepsis." (PMID 17987129, 2007).
Sepsis (continued). "In animal models, HMGB-1 is a mediator of severe sepsis, and an anti-HMGB-1 antibody decreased mortality in the CLP model of sepsis." (PMID 18042296, 2007). "Our recent discovery of HMGB1 as a late mediator of lethal sepsis has prompted investigation for development of new experimental therapeutics." (PMID 17987129, 2007). "HMGB1 is released as a late mediator during acute inflammation and plays a crucial role in the pathogenesis of systemic inflammation in sepsis after the early mediator response has resolved." (PMID 17397533, 2007). "This is the largest prospective study that has been conducted regarding HMGB1 measurements in infections and sepsis." (PMID 17625012, 2007). "HMGB1 has recently been shown to be a proinflammatory cytokine with a role in the immunopathogenesis of sepsis." (PMID 17625012, 2007). "Taken together, these data suggest that EGCG confers protection against lethal sepsis partly by inhibiting HMGB1 cytokine activities." (PMID 17987129, 2007). "This is the first study focusing on HMGB1 levels in a cohort of patients suspected of having community-acquired infections and sepsis and admitted to a department of internal medicine." (PMID 17346334, 2007). "In one small study with 8 healthy people and 25 patients with sepsis, the highest levels of HMGB1 (median 84 ng/ml) were observed in sepsis patients with a fatal outcome." (PMID 17346334, 2007). "In a study using the cecal ligation and puncture (CLP) model of polymicrobial sepsis, HMGB-1 levels increased over the span of 1 to 2 days after CLP and remained elevated during the course of disease." (PMID 18042296, 2007). "Circulating HMGB1 levels are elevated in a delayed fashion (after 16–32 h) in endotoxemic and septic mice, and in patients with sepsis." (PMID 17987129, 2007). "Increased levels of HMGB-1 result in the disruption of endothelial barrier functions, leading to vascular leakage and tissue hypoperfusion, similar to that observed in sepsis." (PMID 16759367, 2006). "HMGB-1 is a late mediator of lethal systemic inflammation in sepsis, however, a recent study has suggested HMGB-1 as an early mediator of inflammation and organ damage in hepatic IR injury." (PMID 16480493, 2006). "Furthermore, during sepsis, macrophages secrete exosomes containing lactylated and acetylated HMGB1; these exosomes can disrupt junctional proteins, such as VE‐Cadherin and Claudin‐5, resulting in endothelial dysfunction." (PMID 41532698, 2026). "It has been confirmed that HMGB1 and histones play an important role in cardiotoxicity in sepsis." (PMID 40356926, 2025). "LPS has been shown to upregulate HMGB1 in rat cardiomyocytes, resulting in negative inotropic effects, and HMGB1 is implicated in facilitating LPS entering cells, and subsequently triggering cell death during sepsis." (PMID 39853914, 2025). "Moreover, HMGB1 is regarded as a crucial predictor of organ dysfunction and outcome in patients with severe sepsis." (PMID 40872555, 2025). "Based on these observations, HMGB1 accumulation in the later stages of sepsis may represent a marker of post-septic immunosuppression and could predict late mortality due to immune paralysis." (PMID 41153764, 2025). "Further supporting the protective role of adiponectin, studies have demonstrated that its administration significantly reduces mortality in septic mice while suppressing levels of IL-6, TNF-α, and high-mobility group box 1 (HMGB1), a key mediator of inflammation and organ damage in sepsis." (PMID 40652274, 2025). "HMGB1 is also correlated with mortality and heart dysfunction in sepsis." (PMID 40406124, 2025). "In murine models of sepsis, high expression of HMGB1 contributes to neutrophil dysfunction by limiting the activation of NADPH oxidase; neutrophils from septic patients, when cultured with plasma and anti-HMGB1, demonstrate a higher capacity to activate NADPH oxidase." (PMID 40364841, 2025).
Sepsis (continued). "Notably, HMGB1 levels were found to increase after IL-6 levels in sepsis, and anti-HMGB1 antibody have been shown to reduce mortality, suggesting HMGB1 as a potential therapeutic target." (PMID 39849347, 2025). "HMGB1 lactation induces acute kidney injury in sepsis by driving the formation of NETs." (PMID 41377071, 2025). "In the context of sepsis, macrophages take up extracellular lactate to instigate HMGB1 lactylation." (PMID 40860191, 2025). "Recent studies have reported the possibility of HMGB1 as a therapeutic target for sepsis." (PMID 40054422, 2025). "Similarly, in sepsis, lactate absorption by macrophages results in the lactylation of the nuclear protein HMGB1, enhancing endothelial permeability via its pro-inflammatory properties." (PMID 39904962, 2025). "In sepsis, macrophage lactate promotes HMGB1 Kla via p300/CBP." (PMID 39897556, 2025). "Importantly, reducing lactate production and/or inhibiting GPR81-mediated signaling in vivo has been found to decrease HMGB1 levels and improve survival outcomes in patients with multimicrobiome sepsis." (PMID 39925738, 2025). "High mobility group protein B1 (HMGB1) is a pro-inflammatory factor that induces a lethal systemic inflammatory response in the late stages of sepsis, and targeting HMGB1 may reduce the impact of sepsis and the associated organ damage." (PMID 40182687, 2025). "As a late‐phase inflammatory mediator, HMGB1 plays a crucial role in sepsis pathophysiology." (PMID 39963819, 2025). "HMGB1 emerges as a promising therapeutic target for the treatment of muscle atrophy in sepsis." (PMID 39963819, 2025). "In terms of miRNA regulatory mechanisms, miR-181c-5p effectively inhibited microglia overactivation in a sepsis model by targeting high mobility group protein B1 (HMGB1), while decreasing the levels of inflammatory factors, such as TNF-α and IL-1β, and decreasing hippocampal neuronal apoptosis." (PMID 40791576, 2025). "Emerging evidence suggests that exosomal biomarkers – proteins like HMGB1, miRNAs such as miR-122, and even lncRNAs/circRNAs – could enhance our ability to diagnose sepsis early, monitor organ damage, and stratify patients for tailored therapies." (PMID 40787977, 2025). "In a murine sepsis model, sodium butyrate reduced the gene expression of high-mobility group box 1, decreased organ damage markers, and improved survival rates, suggesting that sodium butyrate may protect against multi-organ dysfunction in sepsis." (PMID 40284216, 2025). "HMGB1 is also involved in promoting cell death in sepsis, which contributes to muscle degradation." (PMID 39963819, 2025). "In vivo studies further confirmed a reduction in HMGB1-induced mortality in mouse models of sepsis." (PMID 40430897, 2025). "Recently, HMGB1 has been identified as a late-phase inflammatory mediator in sepsis, persisting during prolonged inflammation and contributing to poor outcomes, while cytokines such as IL-6 act as early-phase mediators and play a key role in the cytokine storm associated with BM." (PMID 39849347, 2025). "Suppression of HMGB1 for treatment of sepsis, ischemia, cancer, and autoimmune disorders is currently the focus of multiple clinical trials applying a range of unique HMGB1 antagonists, suggesting significant potential for translation to patients with adenoviral keratoconjunctivitis." (PMID 40367285, 2025). "Hepatocyte GSDMD regulates vascular injury through the release of HMGB1 in sepsis." (PMID 39927458, 2025). "Numerous studies have consistently demonstrated that HMGB1, acting as a “late‐phase” inflammatory mediator, drives the inflammatory cascade in diverse pathologies including trauma, sepsis, radiation‐induced injury, autoimmune diseases, and neurodegenerative disorders." (PMID 41354099, 2025). "Therefore, ferroptosis not only skews macrophages toward the M1 phenotype, intensifying inflammation, but also triggers HMGB1 release, recruiting more immune cells and amplifying the inflammatory response during sepsis." (PMID 41250137, 2025).
Sepsis (continued). "Regarding scavenger molecules, the endogenous protein CD5L is secreted by macrophages and may facilitate clearance of HMGB1 and HSPs in stroke as well as HMGB1 in sepsis according to in vitro studies and mouse models." (PMID 40406124, 2025). "Therefore, calycosin can attenuate sepsis-induced acute lung injury by inhibiting the HMGB1/MyD88/NF-κB pathway and NLRP3 inflammasome activation." (PMID 41463300, 2025). "Interestingly, anti-HMGB1 medication provided many days after severe sepsis can reduce cognitive impairment in mice." (PMID 39466324, 2025). "For instance, HMGB1 not only participates in regulating the production of inflammatory mediators but also promotes the entry of lipopolysaccharides into cells, thereby triggering pyroptosis, which plays a crucial role in sepsis." (PMID 40877572, 2025). "As a molecular marker of liver injury severity during sepsis, HMGB1 Levels were assessed." (PMID 39956880, 2025). "The HMGB1/RAGE signaling pathway regulates vascular injury through endothelial GSDMD in sepsis." (PMID 39927458, 2025). "In a cecal ligation and puncture (CLP)-induced sepsis rat model, calycosin treatment was shown to decrease the levels of HMGB1, MyD88, p-NF-κB, and NLRP3, as well as the contents of pro-inflammatory cytokines such as TNF-α and IL-1β, at the significantly effective dose of 50 mg/kg." (PMID 41463300, 2025). "As HMGB1 is a key mediator of late inflammatory cytokines and severe sepsis, it could be speculated that the protective effect of lidocaine on lung injury may be to decrease the inflammatory level of septic patients by inhibiting the release of HMGB1." (PMID 40338919, 2025). "HMGB1 is highly expressed in patients with sepsis and acute kidney injury." (PMID 41477644, 2025). "In sepsis, although HMGB1 levels in patient serum are markedly elevated, its association with clinical prognosis and specific clinical value remain unclear." (PMID 41296391, 2025). "In the early stage of sepsis, stimuli such as LPS and ROS can trigger the release of HMGB1." (PMID 41244772, 2025). "In a model of CLP-induced sepsis, the “gold standard” rodent model for abdominal sepsis, verbascoside improved survival rates and reduced HMGB1 levels in serum and lung tissue of treated mice, indicating that it may be useful in the treatment of sepsis." (PMID 40724000, 2025). "Extracellular HMGB1 acts as a damage-associated molecular pattern (DAMP) and plays important roles in the pathogenesis of various diseases, such as sepsis, arthritis, inflammatory bowel diseases, fibrotic diseases, diabetes, and malignancies, by activating the innate and adaptive immune response." (PMID 39830661, 2024). "Moreover, following trauma or burns, tissue damage can induce a comparable hyperinflammatory response known as sterile sepsis, mediated by factors such as uric acid, High mobility group box 1(HMGB1), or mitochondrial DNA, among others." (PMID 38612596, 2024). "By targeting HMGB1, it may be possible to attenuate inflammation, reduce tissue damage, and improve outcomes in sepsis." (PMID 38474222, 2024). "HMGB1 is a nuclear protein that plays a crucial role in late immune responses during sepsis." (PMID 39712019, 2024). "Moreover, in the sepsis model induced by LPS, PL has demonstrated significant efficacy in reducing HMGB1 levels and further suppressing proinflammatory cytokines." (PMID 38655086, 2024). "Anti-HMGB1 antibody treatment and specific inhibition of DC secretion of HMGB1 by small interfering RNA (siRNA) of HMGB1 significantly reduce sepsis-induced mortality, which may provide a treatment strategy for sepsis." (PMID 38816685, 2024). "Inhibits release of HMGB1 by macrophages at the end of sepsis." (PMID 38275675, 2024). "Furthermore, lactate levels are positively correlated with HMGB1 concentrations in the blood of sepsis patients." (PMID 39850900, 2024).